FGF21 (fibroblast growth factor 21)
Diseases named in the same sentence as FGF21 in open-access papers (continued):
Sharing a sentence is not in itself a finding about the gene and the disease.
central obesity (continued). "This paradoxical phenomenon led to the hypothesis that central obesity is a state of FGF21 resistance with compensatory FGF1 overproduction resulting from decreased FGF coreceptor (betaKlotho) expression in white adipose tissue." (PMID 32546231, 2020). "Circulating FGF21 decreased significantly after the VLCKD [194.0 (137.6–284.6) to 167.8 (90.9–281.5) p < 0.001] and greater weight loss was predicted by lower baseline FGF21 (Beta = −0.410; p = 0.012), male sex (Beta = 0.472; p = 0.011), and central obesity (Beta = 0.481; p = 0.005)." (PMID 36761216, 2023). "Therefore, the drop in GCs likely decreased insulin levels, which may be another important mechanism that mediates FGF21 LKO to abrogate OVX-induced central obesity in females." (PMID 37834368, 2023). "In this study, we found that circulating FGF21 and GCs were parallelly increased in female mice following OVX treatment and depletion of circulating FGF21 by FGF21 LKO completely reversed high circulating GCs, thus abrogating OVX-induced central obesity in female mice." (PMID 37834368, 2023). "In this study, using OVX mice as a model, we first reported that liver-specific FGF21 knockout (FGF21 LKO) could completely reverse the elevation of circulating GCs and thus abrogate OVX-induced central obesity in mice." (PMID 37834368, 2023). "• Diabetic-exposed offspring had higher BMI, waist circumference and body fat, increased general and central obesity at 9–11 years old. • BMI of O-GDM was 0.89 kg/m2 greater than offspring before their mothers got GDM • O-GDM and O-T1DM had more leptin, less adiponectin and FGF21." (PMID 37255932, 2023). "Serum FGF21 levels in T2DM patients were positively correlated with body shape parameters, including weight, waistline, neck circumference, BMI, ABSI, percent of abdominal obesity, and triglyceride, while negatively with estimated glomerular filtration rate (all p < 0.01)." (PMID 37424900, 2023). "In this study, we first found that liver-specific FGF21 knockout could completely abrogate OVX-induced central obesity by reversing high GC production in mice, highlighting an essential role of hepatic FGF21 in mediating the development of central obesity in estrogen-depleted females." (PMID 37834368, 2023). "In stark contrast, FGF21 LKO completely reversed (p < 0.01) high circulating corticosterone but not high FSH in OVX mice, suggesting the abrogative effect of FGF21 LKO on OVX-induced central obesity was realized via reversing corticosterone production but not FSH in females." (PMID 37834368, 2023).
lipid metabolism disorders (13 papers, 2016 to 2025). "NRS (400 mg/kg daily) ameliorates high-fructose-induced lipid metabolism disorder in C57BL/6J mice via improving fibroblast growth factor 21 (FGF21) resistance in the liver and WAT." (PMID 37630330, 2023). "A study demonstrated that the administration of exogenous FGF21 significantly improved lipid metabolic disorders and reduced atherosclerotic plaque areas in animal models." (PMID 34513950, 2021). "Strong evidence identified that administration of exogenous FGF21 significantly improved lipid metabolic disorders and reduced atherosclerotic plaque areas in these animals." (PMID 27247947, 2016). "Interestingly, FGF21 appears to have similar mechanisms to lipid metabolism disorders in T2DM with HP." (PMID 37424900, 2023). "Recent investigations have additionally identified an imbalance in the fibroblast growth factor 21 (FGF21) and MAPK1 signaling axes as key determinants of hepatic lipid metabolism disorders during ketosis." (PMID 41463929, 2025). "Studies on the relationship between WAT and an FGF21 pharmacological action in metabolism regulation concluded that the therapeutic effect of FGF21 on carbohydrate and lipid metabolism disorders is independent of the transformation of white into brown adipose tissue." (PMID 30927227, 2019). "By stimulating the sirtuin 1 (SIRT1)/peroxisome proliferator-activated receptor alpha (PPARα)/Fibroblast growth factor 21 (FGF21) pathway, APS could alleviate lipid metabolism disorder, notably, by increasing hepatic glycolipid metabolism, reducing inflammation, and lipid droplet deposition." (PMID 35308224, 2022).
malnutrition (13 papers, 2011 to 2025). Inadequate nutrition resulting from poor diet, malabsorption, or abnormal nutrient distribution. "Under nutritional deficiency, fibroblast growth factor-21 (FGF21) signaling activates the global expression of autophagy-related genes through the histone H3K27-ME3 demethylase Jumonji-D3 (JMJD3/KDM6B), thus mediating lipid degradation." (PMID 37762347, 2023). "Given the high variability in inter-individuals and interspecies, further studies are urgently needed to evaluate the legitimate therapeutic roles of FGF15/19 and FGF21 in malnutrition associated diseases." (PMID 26931208, 2016). "The disturbances in FGF21 secretion may contribute to the multifactorial pathogenesis of malnutrition and weight loss in IBD patients." (PMID 38983722, 2024). "We speculate that the FGF21-NE pathway may also heighten arousal and alertness in order to increase foraging during periods of nutritional deficiency." (PMID 36889282, 2023). "Since malnutrition which referred to deficiencies in energy or nutrient uptake commonly caused growth retardation, we tested expression levels of hepatic Fgf21 and Sirt1, key genes for Igf1 inhibition under malnutrition condition." (PMID 40598150, 2025). "Contrary, an increase in FGF21 level during the active phase of IBD exerts negative metabolic effects contributing to malnutrition and weight loss and exacerbating inflammation." (PMID 38983722, 2024). "Mitokines (Humanin (HN), GDF15 and FGF21) are produced as a result of mitochondrial dysfunction and may have major roles in chronic inflammation, malnutrition and exercise capacity in people with COPD." (PMID 36243733, 2022). "Therefore, the multifactorial pathogenesis of malnutrition and weight loss in IBD patients may be related to disturbances in FGF21 level." (PMID 38983722, 2024). "Our data concurs with these previous observations on the negative relationship between FGF21 and tryptophan, which was independent of malnutrition in early life." (PMID 33238545, 2020).
carotid atherosclerosis (12 papers, 2015 to 2025). A thickening and loss of elasticity of the walls of carotid arteries that occur with formation of atherosclerotic plaques. "Our research team previously revealed that FGF21 was associated with type 2 diabetes (T2D) and carotid atherosclerosis based on the data from Hong Kong Cardiovascular Risk Factor Prevalence Study (CRISPS)." (PMID 40356318, 2025). "In a cohort of 670 subjects who underwent carotid intima-media thickness (IMT) measurements, elevated circulating FGF21 was associated with a higher risk of carotid atherosclerosis." (PMID 35369322, 2022). "We demonstrated that FGF21 was significantly associated with carotid atherosclerosis." (PMID 40356318, 2025). "As male participants in our study had a higher prevalence of smoking and higher serum levels of TG, the impact of FGF21 on carotid atherosclerosis might be outweighed by these confounding risk factors." (PMID 26047614, 2015). "In men, likely FGF21 affects inflammation and lipids, which is known to play a significant role toward the development of carotid atherosclerosis." (PMID 33996935, 2021). "Another study involving 670 patients also demonstrated a positive association between serum FGF21 levels and carotid atherosclerosis, independent of lipid levels." (PMID 37576954, 2023). "Furthermore, elevated circulating FGF21 levels also found in patients with carotid atherosclerosis, subclinical atherosclerosis, CHD, and acute MI." (PMID 36180826, 2022). "Addition of CRP as a covariate in the model also did not change the results in the female subgroup, showing that FGF21 associated with carotid atherosclerosis independent of CRP concentrations or inflammation." (PMID 33996935, 2021). "Elevated serum FGF21 levels are also seen in subjects with coronary heart disease (CHD) and in patients with carotid atherosclerosis." (PMID 26594197, 2015).
cognitive decline (12 papers, 2018 to 2025). "In fact, FGF21 treatment has been suggested as an option for improving cognitive decline associated with neurodegeneration." (PMID 38673797, 2024). "This specific association suggests that in ME, FGF-21 may exert a beneficial effect on brain function, potentially serving as a buffer against cognitive decline." (PMID 40868993, 2025). "Study of obese, insulin resistant rat model illustrated the effect of FGF‐21 on prevention of cognitive decline which is associated with its abilities to improve hippocampal synaptic plasticity, dendritic spine density, brain mitochondrial function, and attenuate brain cell apoptosis." (PMID 34379890, 2021). "FGF21 has been implicated in the inhibition of cognitive decline and fibrogenesis." (PMID 32483404, 2020). "On the contrary, there was a trend toward cognitive decline with high CSF FGF21 levels in individuals aged >34 years old." (PMID 40792551, 2025). "Fibroblast growth factor 21 (FGF21) is a hormone secreted under mitochondrial stress and has been associated with cognitive decline in AD." (PMID 39996748, 2025). "Furthermore, FGF21’s neuroprotective benefits were associated with a rapid increase in phosphorylation in Akt1 and other signaling pathways, which may aid in amelioratory cognitive decline." (PMID 32267096, 2020). "The findings of this study suggest that increased FGF21 in non-elderly MetS patients is associated with cognitive decline." (PMID 29581470, 2018). "Additionally, a recent study found that obese-insulin resistant rats have developed an impairment of brain FGF21 signaling with increased serum/brain FGF21 levels, and cognitive dysfunction, suggesting the occurrence of brain FGF21 resistance which might lead to cognitive decline in this condition." (PMID 33850218, 2021). "However, the correlation between FGF21 and cognitive decline in elderly and nonelderly MetS patients has not been investigated." (PMID 29581470, 2018).
Alzheimer disease (11 papers, 2019 to 2025). A progressive, neurodegenerative disease characterized by loss of function and death of nerve cells in several areas of the brain leading to loss of cognitive function such as memory and language. "To investigate this further, we aimed to leverage human genetic data within the Mendelian randomization paradigm to investigate the associations of a common allele in the FGF21 gene with cardiometabolic outcomes, Alzheimer’s disease and lifespan." (PMID 33946944, 2021). "In animal models, FGF21 has been shown to have beneficial effects on cardiometabolic outcomes, Alzheimer’s disease risk and lifespan." (PMID 33946944, 2021). "In summary, we used a major allele of rs838133 in the FGF21 gene to identify evidence for its effects on macronutrient and alcohol intake as well as favourable effects on a range of cardiometabolic outcomes, Alzheimer’s disease and lifespan." (PMID 33946944, 2021). "We also identified a potential beneficial effect of the major allele at FGF21 rs838133 on cardiovascular outcomes, with the strongest association for venous thromboembolism, as well as on Alzheimer’s disease and lifespan." (PMID 33946944, 2021). "Furthermore, FGF21 has been implicated in protecting against Alzheimer’s disease, as well as improving lifespan." (PMID 33946944, 2021). "The FGF21 G allele was associated with lower intakes of total sugars and alcohol, and higher intakes of protein and fat as well as favourable with lipid levels, blood pressure traits, waist-to-hip ratio, systemic inflammation, cardiovascular outcomes, Alzheimer’s disease risk and lifespan." (PMID 33946944, 2021). "Moreover, a decrease in FGF21 levels was identified in the serum of individuals diagnosed with Parkinson's disease and Alzheimer's disease." (PMID 39744501, 2025). "Furthermore, the contribution of metabolic disturbances in glucose homoeostasis and insulin insensitivity is well recognized in Alzheimer's’ disease, and FGF21 may have the utility to reverse that component of pathogenesis." (PMID 30802174, 2019).
Cachexia (11 papers, 2021 to 2026). Severe weight loss, wasting of muscle, loss of appetite, and general debility related to a chronic disease. "FGF21 was the only biomarker independently associated with cachexia (odds ratio, 1.71; 95% CI, 1.10-2.66; p = 0.016)." (PMID 41788683, 2026). "Although the involvement of FGF21 in cancer cachexia needs to be further investigated, a clinical study reported high FGF21 serum levels in elderly patients with cachexia." (PMID 35646636, 2022). "For instance, FGF21 can affect food intake, appetite, or food preference, and GDF15 which can also be released from autophagy-deficient tumors can induce cachexia associated with cancer." (PMID 35321438, 2022). "Although the involvement of FGF21 in cancer cachexia needs to be further investigated, a clinical study has confirmed a correlation of FGF21 with cachexia in elderly patients." (PMID 33925872, 2021). "The endocrine factor FGF21 modulates appetite and is involved in cachexia." (PMID 37370867, 2023). "The serum level of FGF-21 was marked higher and correlated with cachexia in old age patients." (PMID 33810243, 2021). "Taken together these observations point to the possibility that plasma FGF21 levels are not a mediator of the profound cachexia observed in FGF15INT-KO VSG mice and are increased in response to the muscle mass loss and/or hepatic lipid accumulation in these mice." (PMID 34362888, 2021).
COVID-19 (11 papers, 2021 to 2025). A disease caused by infection with severe acute respiratory syndrome coronavirus 2. "Fibroblast growth factor 21, proposed as a biomarker of mitochondrial dysfunction, was also shown to be associated with COVID-19 severity and mortality." (PMID 41226417, 2025). "Another growth factor upregulated in this group of patients was FGF21, which is linked to mitochondrial dysfunction in peripheral blood mononuclear cells (PBMCs) which drives a systemic immune response in COVID-19 pathogenesis." (PMID 37047248, 2023). "Of note, FGF21 was reported to induce ACE2 expression in adipocytes and renal cells in mouse models, which led to our hypothesis that FGF21 upregulation might cause aggravation of COVID-19 via induction of ACE2 in various lifestyle-related diseases." (PMID 36035417, 2022). "Obese patients with COVID-19 also had increased levels of FGF-21 compared with overweighted ones, especially those diagnosed with MetS." (PMID 37408184, 2023). "Contrary to our observations, they demonstrated an increase in FGF-21 levels in patients with COVID-19 compared to HC (p < 0.001)." (PMID 34680053, 2021). "We analyzed the relationships between PTX3, FGF-21, fetuin-A, and irisin levels and COVID-19 severity, concomitant metabolic abnormalities, and liver injuries." (PMID 34680053, 2021). "The serum concentration of FGF-21 was significantly increased in obese COVID-19 patients compared to overweight ones." (PMID 34680053, 2021). "Serum concentration of FGF-21 was significantly increased in obese COVID-19 patients compared to overweight ones (529.9 (379.3–708.3) vs. 157.6 (62.5–307.7) pg/mL; p = 0.001, respectively)." (PMID 34680053, 2021). "Regarding a hypothetical relationship of FGF-21 with the severity of COVID-19 course in our study, we could discern significantly positive correlation in this hepatokine levels and such inflammation markers as ferritin or IL-6." (PMID 34680053, 2021). "COVID-19 patients with higher ferritin levels showed increased FGF-21 and PTX3 concentrations." (PMID 34680053, 2021). "We did not observe any differences in FGF-21 concentration between COVID-19 patients with and without iron deficiency." (PMID 34680053, 2021). "A recent study determined that patients with asymptomatic SARS-CoV-2 infection had higher values of fibroblast growth factors (including FGF19, FGF21, and FGF23) compared to those with mild symptomatic COVID-19." (PMID 36828412, 2023). "CCL23, among the other seven proteins (IL-17C, MMP-10, FGF-19, FGF-21, FGF-23, and CXCL5), was higher in asymptomatic COVID-19 patients than in patients with symptoms." (PMID 37834869, 2023). "They noticed a trend of high levels of FGF-21 and an increase in COVID-19 severity among patients who were admitted to ICU (p < 0.001) and died due to COVID-19 (p = 0.001)." (PMID 34680053, 2021). "However, the robust study design and statistical analysis as well as the consistencies with previous studies, such as the upregulation in patients with COVID-19 of ACE2, FGF21, CCL26 and VWF among others, suggest the potential validation of these novel findings." (PMID 37047248, 2023).
dyslipidaemia (11 papers, 2013 to 2025). "Further, Pegbelfermin (BMS-986036), a PEGylated human FGF21 analogue, ameliorated dyslipidaemia, increased adiponectin levels, and decreased the levels of fibrosis markers in T2DM patients." (PMID 36362103, 2022). "Recently, a FGF21 analogue has been shown to improve dyslipidaemia in obese people, however only a trend toward glucose lowering was observed." (PMID 24619218, 2014). "At the end of the 28-day treatment period, the usage of FGF21 analogue produced favourable effects on circulating lipid profiles (triglycerides, low-density lipoprotein cholesterol and high-density lipoprotein cholesterol) and contributed to improvements in dyslipidaemia." (PMID 40356318, 2025).